SMAD2 (SMAD family member 2)
Diseases named in the same sentence as SMAD2 in open-access papers (continued):
Sharing a sentence is not in itself a finding about the gene and the disease.
Myocardial fibrosis (continued). "To verify the possible signaling pathway involved in myocardial fibrosis of diabetic heat, we analyzed the expression of TGF-β/Smad2/3 by immunohistochemistry." (PMID 33829019, 2021). "Taken together, the present study demonstrated that LQ ameliorated ISO-induced myocardial fibrosis in a mouse model and inhibited the apoptosis of cardiomyocytes in vitro by inhibiting both the TGF-β1/Smad2 and AKT/ERK signaling pathways." (PMID 34328199, 2021). "The present study demonstrated that LQ attenuated myocardial fibrosis in mice and cultured myocardial cells via regulating the TGF-β1/Smad2 and AKT/ERK signaling pathways, suggesting the protective effects of LQ on cardiac fibrosis." (PMID 34328199, 2021). "Overall, hyperglycaemia up‐regulated miR‐21, followed by down‐regulation of its target SMAD7, which, in turn, enhanced the phosphorylation of SMAD2 and SMAD3, thereby promoting EndMT activation and myocardial fibrosis." (PMID 31680453, 2020). "In the present study, TRPM7 expression was increased in SAN tissues in SSS rats together with a significant increase in Smad2 phosphorylation level, suggesting the involvement of TRPM7/Smad2 in Ang II-mediated myocardial fibrosis." (PMID 29511803, 2018). "Ang II infusion significantly increased myocardial fibrosis, expression of collagen I, collagen III, and TGF-β1, as well as TGF-β1 downstream proteins p-Smad2, p-Smad3, TRAF6, and p-TAK1 (all p<0.05)." (PMID 30175152, 2018). "Specifically, SR-717 administration aggravated cardiac insufficiency in DOX-treated GsdmeCKO mice, and the attenuation of myocardial fibrosis, collagen deposition, and abnormal TGF-β/SMAD2/SMAD3 activation in DOX-treated GsdmeCKO mice was suppressed by SR-717 administration." (PMID 41208882, 2025). "Through CD63 (TIMP1 cell-surface receptors), TIMP1 and integrin beta 1 could promote activation and nuclear transfer of Smad2/3 and the beta serial protein, resulting in the deposition of types I and III collagen and subsequently myocardial fibrosis." (PMID 38728374, 2024). "Thus, increased expressions of SMAD2 and SMAD3 contributed to myocardial fibrosis in patients with HOCM, which happened early in childhood and continued through adulthood." (PMID 36878974, 2023). "On the other hand, a hypothyroid state may directly induce myocardial fibrosis via stimulating autophagy and inhibiting TGF-β1/Smad2 signal transduction pathway." (PMID 37239123, 2023). "This balance and the unaltered levels of phosphorylated SMAD2/3 are also in line with the absence of myocardial fibrosis, as BMPR2 is an antagonist in the TGFβ fibrotic pathway, preventing fibrosis." (PMID 33716758, 2021). "In conclusion, we speculate that Smad7 may have mediated the interaction between TGF-β/Smad2/3 and Wnt/β-catenin in the TSF treatment of myocardial fibrosis." (PMID 34938743, 2021). "Also, many signaling pathways are involved in myocardial fibrosis, but we only studied the effect of TRPM7 on collagen synthesis in the myocardium through Ang II/Smad2 signaling." (PMID 29511803, 2018). "Previously, we have showed that GXD ameliorated heart injury and protected rats from myocardial fibrosis, which may be related to inhibiting the TGF-β1 signaling pathway by down-regulating expressions of Smad2/3 whereas improving Smad7 expression." (PMID 26846090, 2016). "In conclusion, we provide evidence that GYY4137 decreases myocardial fibrosis, which may be related to inhibition of oxidative stress, blockage of TGF-β1/Smad2 signaling pathway, and decrease in expression of α-SMA in cardiac fibroblasts." (PMID 26078813, 2015). "Moreover, some representative phenols and phenolic acids such as salvianolic acid A, salvianolic acid B, ferulic acid and curcumin etc can be used for the treatment of myocardial fibrosis through inhibition of Ras homolog gene family member A (RhoA)/ROCK and TGF-β1/Smad2 signaling pathways." (PMID 38444481, 2024).
Myocardial fibrosis (continued). "GYY-4137 was also supposed to protect against myocardial fibrosis in SHR, which may be related to the inhibition of oxidative stress, the blockage of transforming growth factor β1 (TGF-β1)/Smad2 signaling pathway, and the decrease in the expression of α-smooth muscle actin in cardiac fibroblasts." (PMID 36012477, 2022). "Interestingly, the deletion of Smad2 alone did not affect adverse myocardial fibrosis, while Smad3 seemed to be indispensable to the pressure-overload-induced fibrotic response." (PMID 34572061, 2021). "Thus, the cardioprotection of SFI treatment in CHF for myocardial fibrosis may be achieved by upregulation of Smad7 and downregulation of TGF-β1, Smad2, and Smad3 gene expression via TGF-β/Smads signaling pathway." (PMID 28698735, 2017). "These evidences suggested that BMSCs may reduce the expression of TGF-β1 to ameliorate myocardial fibrosis, but this effect may not entirely depend on the p-Smad2 signaling pathway." (PMID 29362568, 2017). "Massive endeavors were made to relive or reverse myocardial fibrosis, but the effect of those treatment strategies was failed because targeting TGF-β1, SMAD2/3, or TβRI/II directly will be ended up with poor outcomes like autoimmune diseases, heart failure, or unknown risks." (PMID 34483923, 2021).
fibrosis (55 papers, 2013 to 2026). the formation of excess fibrous connective tissue in an organ or tissue in a reparative or reactive process. "This suggests that OTA causes intestinal fibrosis via TGF-β/Smad2/3 signaling pathway with miR-155-5p regulation." (PMID 37505742, 2023). "The cytokine TGF-β mediates tissue fibrosis associated with inflammation and tissue injury, fibroblast-specific TGF-β-SMAD2/3 signaling underlies cardiac fibrosis." (PMID 35136033, 2022). "Other studies have shown that theincrease in cardiac fibrosis observed in male patients with severe AS is relatedto increased SMAD family member 2 (SMAD2) phosphorylation and TGF-β1protein expression." (PMID 40927094, 2025). "The SMAD-2, -3, and -4 gene expression levels were higher in the fibrosis group compared to the other groups." (PMID 39055873, 2024). "Consistent with cardiac fibrosis, Lamin A transduced hearts showed a significant upregulation of p-Smad2 and the myofibroblast marker αSMA." (PMID 37840136, 2023). "Although additional research is required to fully understand Smad2 and Smad3 involvement in intestinal fibrosis, it is reasonably inferred that TGF-β is involved in intestinal fibrosis development, as well as in other organs." (PMID 37505742, 2023). "Ultrasound point shear wave elastography and assessment of TGF-β1 and p-Smad2/3 expression can reflect the degree of MTrPs fibrosis to some extent." (PMID 38077437, 2023). "Ultrasound point shear wave elastography, TGF-β1 and p-Smad2/3 can reflect the degree of MTrPs fibrosis to some extent." (PMID 38077437, 2023). "The dysregulation of TGF-β1/Smad pathway was an important pathogenic mechanism in tissue fibrosis and Smad2 and Smad3 are the two major downstream regulator that promote TGF-β1-mediated tissue fibrosis." (PMID 33896391, 2021). "Fibrosis, one of the major causes of morbidity and mortality in ALMS, is primarily driven by TGF-β ligands, especially activators of the SMAD2/3 axis, which is upregulated in many human fibrotic conditions." (PMID 33598462, 2021). "TRPV3 channel induces dermal fibrosis via the TRPV3/TSLP/ mothers against decapentaplegic homolog 2/3 (Smad2/3) pathways in dermal fibroblasts." (PMID 32485929, 2020). "CXCL4 promotes cardiac fibrosis through activating the TGF‐β1/Smad2/3 signaling pathway." (PMID 38577984, 2024). "In addition, CXCL4 promotes cardiac fibrosis through activating the TGF‐β1/Smad2/3 signaling pathway." (PMID 38577984, 2024). "Notably, 3PO reduced PFKFB3 expression and inhibited the transforming growth factor-beta 1/mothers against the decapentaplegic homolog 2/3 (TGF-β1/SMAD2/3) signaling pathway to inhibit cardiac fibrosis after MI." (PMID 37509108, 2023). "In addition to these classic factors in the cascade, multiple players involved in the TGF-β/ALK5/Smad2/3 signaling pathway also modulate cardiac fibrosis." (PMID 35461308, 2022). "Anti-E2F1 might be a better strategy for cardiac fibrosis than intervening TGF-β–Smad2/3 signaling pathway directly." (PMID 34521301, 2021). "Therefore, we have set the stage for future research focus on a causal link between the observed downregulation of miRNAs and the changes in the expression of TGF-β1, Smad2, Smad3, and Smad7 mRNA, involved in cardiac fibrosis and remodeling." (PMID 28698735, 2017). "Therefore, Meox1/Cthrc1/p-Smad2/3 signaling pathway might be a promising therapeutic target for cardiac fibrosis and remodeling in MI patients." (PMID 41362745, 2026). "Therefore, Smad3 and Smad2 play a distinct role in cardiac fibrosis in the infarcted heart." (PMID 37449045, 2023). "Therefore, leonurine might improve cardiac fibrosis induced by isoprenaline by inhibiting pyroptosis via the TGF-β/Smad2 signalling pathway." (PMID 36327230, 2022).
fibrosis (continued). "We did not observe any difference at the mRNA level of SMAD2 in WWP2Mut/Mut cardiac (myo)fibroblasts or in cells overexpressing or silencing the WWP2-N/FL isoforms, suggesting that WWP2 function on cardiac fibrosis could be exerted through SMAD2 interaction and ubiquitination at the protein level." (PMID 31399586, 2019). "Notable reductions in the cardiac fibrosis area, collagen deposition, and TGF-β/SMAD2/SMAD3 activation were also observed in DMF-treated DIC model mice." (PMID 41208882, 2025). "R-Smads include Smad2, Smad3, Smad1, Smad5, and Smad8, with Smad2 and Smad3 being the key downstream mediators of TGF-β-induced tissue fibrosis." (PMID 40655154, 2025). "CCR2+ macrophage depletion markedly suppressed myocardial fibrosis, collagen deposition, and aberrant TGF-β/SMAD2/SMAD3 signaling activation in the hearts of DIC mice." (PMID 41208882, 2025). "Together, we found that CXCL4 promotes cardiac fibrosis in VMC mice and relies on the activation of the TGF‐β1/Smad2/3 signaling pathway." (PMID 38577984, 2024). "The SMAD2, SMAD3, and SMAD4 mRNA expression levels were increased and the SMAD7 mRNA expression level was decreased in the fibrosis control group." (PMID 39055873, 2024). "In the current study, the SMAD2, SMAD3, and SMAD4 mRNA expression levels were determined to be increased, and the SMAD7 mRNA expression level was decreased in the fibrosis control group." (PMID 39055873, 2024). "Numerous studies support our findings, showing that ISO induces cardiac fibrosis and plays a role in the upregulation of TGF-β/Smad2/Smad3 expression in cardiac tissues in a rat model of ISO-induced MI." (PMID 36964489, 2023). "Being a pivotal regulator of cardiac fibrosis, transforming growth factor-β1 (TGF-β1) binds to TGFβ receptor on plasma membrane and thus mediates phosphorylation of Smad2/3." (PMID 36327404, 2022). "Smad2/3 are key regulators of the fibrogenesis process in cardiac fibroblasts, whereas silencing METTL3 reduced the upregulation of Smad2/3 induced by TGF-β1, suggesting that METTL3 regulated cardiac fibrosis at least partially through Smad-mediated pathway." (PMID 35224032, 2022). "In contrast, the expression levels of cardiac fibrosis-related proteins such as MMP-2/9, TGF-β1, and p-Smad2/3 in the hearts of MI rats were higher than those in sham hearts." (PMID 30050588, 2018). "Interstitial fibrosis, increased expression of α-smooth muscle actin (SMA) and transforming growth factor (TGF)-β1 and phosphorylation of Smad2/3 were induced by ureteral ligation; however these effects were abrogated by intermediate and high doses of AA." (PMID 24137256, 2013). "In many fibrotic diseases, TGF-β1 combines with type I receptors, type II receptors and relays signal transduction through phosphorylation of downstream effectors, such as Smad2/3, to promote MMP expression and collagen deposition, eventually lead to tissue fibrosis." (PMID 36686225, 2022). "Neither Smad2 nor Smad3 expression was affected, but p-Smad2 and p-Smad3 were both significantly increased in the fibrosis model groups." (PMID 28839277, 2017).
glioma (50 papers, 2012 to 2025). A benign or malignant brain and spinal cord tumor that arises from glial cells (astrocytes, oligodendrocytes, ependymal cells). "Based on these studies and the results of the present study, we hypothesized that the differences in the molecular structures of Smad2 and Smad3 may be the reason underlying why Smad3 has a significant effect on the regulation of TGFβ2-induced cell proliferation in glioma cells." (PMID 25891822, 2015). "TREM1 is preferentially expressed by M2-like TAMs and induces a mesenchymal-like state in glioma stem cells (GSCs) by modulating the secretion of TGFβ2, thereby activating the TGFβR/SMAD2/3 signaling pathway in GSCs." (PMID 41394801, 2025). "After silencing PSMB8, reduced expression of TGFBR1 and TGFBR2 led to decreased phosphorylation of SMAD2/3, which inhibited the malignant behavior of glioma cells." (PMID 40335825, 2025). "Our study showed that ITGB8-TGFβ1 affected downstream activation of Smad2/3 and RhoA in glioma cells." (PMID 35676251, 2022). "The TGFβ/Smad pathway is a recognized signal pathway that promotes the progression of glioma, characterized by p-Smad2 nuclear translocation." (PMID 35992200, 2022). "According to the gray value calculation, the downregulation of TGF-β1, TGF-β2, Smad4, and p-Smad2 protein levels in the siRNA1 and siRNA2 groups was statistically significant compared to controls in U87 glioma cells (p < 0.05)." (PMID 35571491, 2022). "The protein levels of TGF-β1, TGF-β2, Smad4, and p-Smad2 in the siRNA1 and siRNA2 groups were significantly downregulated compared to the siNC group in U87 glioma cells." (PMID 35571491, 2022). "Overexpression of the long noncoding RNA TCONS_00020456, which targets the Smad2/PKCα axis, reduced glioma cell proliferation, migration, and invasion and inhibited epithelial–mesenchymal transformation and glioma progression in vivo." (PMID 36358843, 2022). "The results also indicated that MICAL2 binded with TGFRI and promoted EMT-like process of glioma cells through TGFRI/p-Smad2 signaling pathway." (PMID 34868922, 2021). "At first, we found that the expression levels of TGF-β and MICAL2 were higher in high-grade glioma cells and that MICAL2 was associated with higher p-Smad2 upon evaluation, using immunohistochemistry." (PMID 34868922, 2021). "The immunohistochemical result showed that the expression of TGF-β, MICAL2, and p-Smad2 was increased with the grade of glioma." (PMID 34868922, 2021). "The expression of TGF-β, MICAL2, and p-Smad2 in different-grade gliomas was analyzed using immunohistochemistry." (PMID 34868922, 2021). "In glioma cells, the activation of autophagy by rapamycin treatment increases the expression levels of Smad2/3 and decreases the expression levels of Smad7, leading to TGF-β pathway activation." (PMID 32164764, 2020). "The ALK5 inhibitor SD-208 inhibits TGFβ-induced VEGF expression with inhibition of SMAD2 phosphorylation in glioma cell lines." (PMID 31662989, 2019). "Overall, we observed 956 genes differentially expressed between the SMAD1(+) and SMAD2(+) glioma cell populations (Bonferroni-adjusted P < 0.05); 671 genes were upregulated in SMAD2+ cells, while 285 were upregulated in SMAD1(+) cells." (PMID 31602000, 2019). "SMAD2+ glioma cells were highly enriched for the DNA polymerase factor, PCNA, consistent with the conclusion that this cell population housed the majority of dividing cells." (PMID 31602000, 2019). "It has been shown that the TGFβ level is elevated in higher grades of gliomas and its signaling pathway regulates tumor progression through phosphorylation of SMAD2 and SMAD3, which form a complex with SMAD4 to regulate target gene transcription." (PMID 29861845, 2018). "A key signaling molecule that is highly enriched in the glioma microenvironment is the Transforming Growth Factor-beta (TGFβ) which activates the TGFβ pathway that is mediated by SMAD2 and 3, substrates for the TGFβ family of receptors." (PMID 29861845, 2018).
glioma (continued). "Nrp1-deficient or EG00229-treated wild-type microglia exhibited a shift towards anti-tumorigenicity as evident by altered inflammatory marker profiles in vivo and decreased SMAD2/3 activation when conditioned in the presence of glioma-derived factors." (PMID 26755653, 2016). "The present study investigated how downregulation of the expression levels of Smad2 and Smad3 affected glioma cell proliferation." (PMID 25891822, 2015). "The results revealed that the knock down of Smad2 and Smad3 enhanced cellular proliferation, demonstrating that Smad2 and Smad3 had an inhibitory effect on cell proliferation in this glioma cell line." (PMID 25891822, 2015). "Previous studies have investigated the expression levels of Smad2 and Smad3 in gliomas in tumor specimens and cell lines, however, the results have been inconsistent." (PMID 25891822, 2015). "The results revealed that the protein expression levels of Smad2 and Smad3 were lower in the glioma cell lines compared with normal astrocytes." (PMID 25891822, 2015). "Nevertheless, these data are controversial to a study in which higher phospho-SMAD2 (p-SMAD2) level correlated with higher grade of glioma." (PMID 22943793, 2012). "Furthermore, decreased PFS and OS correlate with elevated concentrations of the substrate of TGF-β receptor I (TβRI), phosphorylated SMAD2 (p-SMAD2), in contrast to the concentrations in glioma patients with lower levels." (PMID 38534215, 2024). "For example, TGF-β-treated U87 and U251 glioma cells undergo mesenchymal-like transformation through the induction of the Smad2 signaling pathway, leading to morphological changes, up-regulation of mesenchymal markers, and increased glioma cell invasion and migration." (PMID 38154100, 2023). "We utilized these compounds for in vitro assessment of SMAD2/3 following Nrp1 inhibition and activation in WT and Nrp1-KO microglial cell lines in the presence and absence of glioma associated cytokines." (PMID 36203599, 2022). "Then, TGF-β/Smad pathway-related protein expression was measured in clinical glioma samples, results of which revealed upregulation of TGF-β and increased extent of Smad2/3 phosphorylation in glioma samples, while the increase tended to be more significant over the glioma stages." (PMID 35275031, 2022). "Endothelial cells might provide large amounts of sTβRIII within the tumor to promote TGF-β2/Smad2 signaling in glioma cells and thereby promote tumorigenicity." (PMID 33772427, 2021). "Yet little was known about the molecular and cellular mechanisms by which FMOD expression is regulated, and only one study has been reported which suggested that FMOD transcription in glioma cells is positively regulated by the TGF-β1/SMAD2 pathway by an epigenetic mechanism." (PMID 31824307, 2019). "To further understand the role of APOBEC3G in Smad2 deactivation in gliomas, we determined its role in mediating the expression of the Smad2-targeted genes Thrombospondin 1 (TSP-1), matrix metallopeptidase 2 (MMP2) and TIMP metallopeptidase inhibitor 1 (TIMP-1)." (PMID 28903341, 2017). "We show here that Nrp1MgKO microglia fail to activate SMAD2/3 signaling in response to glioma tumor cell-conditioned media that contains TGFβ in addition to other cytokines, and that this altered combination of signaling pathways underlies their increased M1, anti-tumoral polarization." (PMID 26755653, 2016). "However, the relative involvement of Smad2 and Smad3 in the control of TGFβ2-induced cell proliferation in glioma cells remains to be elucidated." (PMID 25891822, 2015). "Similarly, the positive p-Smad2 expression was reported to be correlated with tumor proliferation and poor prognosis in a study of 52 patients with glioma." (PMID 25373709, 2014).